RNY3P1 (RNY3 pseudogene 1)
Gene: Miscellaneous RNA gene on chromosome 5 (79,170,234 to 79,170,335, reverse strand). Ensembl gene ENSG00000201955.
Homologues: Orthologues: chimpanzee Y_RNA (100% identical), guinea pig Y_RNA (94% identical). Paralogues in human: RNY3 (96% identical), Y_RNA (95% identical), Y_RNA (94% identical), Y_RNA (93% identical), Y_RNA (92% identical), RNY3P11 (91% identical), Y_RNA (91% identical), Y_RNA (90% identical), Y_RNA (89% identical), RNY3P14 (88% identical), Y_RNA (88% identical), RNY3P16 (87% identical), and 99 more.
Diseases named in the same sentence as RNY3P1 in open-access papers:
RNY3P1 is named in the same sentence as 1 disease in open-access papers, as found by Europe PMC text mining. Sharing a sentence is not in itself a finding about the gene and the disease. The quoted sentences say what the papers report.
melanoma (2 papers, 2020 to 2023). A malignant, usually aggressive tumor composed of atypical, neoplastic melanocytes. "RNY3P1, RNY4P1, and RNY4P25 show significantly higher expression in stage 0 human melanoma than at more advanced stages." (PMID 37835660, 2023).